TOB2P1 (transducer of ERBB2, 2 pseudogene 1)
Synonyms: TOB4p; p373c6.3; formerly TOB2P
Gene: Processed pseudogene on chromosome 6 (28,217,643 to 28,218,634, reverse strand). Ensembl gene ENSG00000176933.
Diseases named in the same sentence as TOB2P1 in open-access papers:
TOB2P1 is named in the same sentence as 1 disease in open-access papers, as found by Europe PMC text mining. Sharing a sentence is not in itself a finding about the gene and the disease.
TOB2P1 shares sentences with these, for which no sentence is quoted: tumor (1 paper).